AR (androgen receptor)
Diseases named in the same sentence as AR in open-access papers (continued):
Sharing a sentence is not in itself a finding about the gene and the disease.
breast carcinoma (continued). "Successful treatment with anti-androgen therapy in other androgen receptor-positive malignancies such as prostate and breast cancer has inspired researchers to investigate this treatment in salivary gland cancer as well." (PMID 28208703, 2017). "The repressive function of C1orf64 on AR transcriptional activity suggests that C1orf64 acts a negative regulator of AR function in breast cancer cells." (PMID 28915724, 2017). "Currently, AR expression in breast cancer is defined on the basis of immunohistochemical (IHC) staining." (PMID 28957377, 2017). "Our data suggest that AR acts in a distinctive mechanism to promote the growth of HER2 + breast cancer cells." (PMID 29109513, 2017). "There was a strong correlation between androgen receptor RNA and protein expression across all breast cancer subtypes (R2 = 0.72, p < 0.01)." (PMID 28840192, 2017). "In this paper we review the literature on the biology of AR in breast cancer and its prognostic and predictive roles." (PMID 28245550, 2017). "In this study, we have discussed multiple molecular mechanisms that we believe are central to the understanding of the overall contributions of AR in breast cancer and its metastasis in post-menopausal women." (PMID 29254284, 2017). "Emerging data suggest that nuclear expression of the androgen receptor (AR) can be detected in 12–55% of triple-negative (ER-/PR-/HER2-) breast cancer." (PMID 29276709, 2017). "Consistent with previous work showing that curcumin suppresses androgen receptor expression in breast cancer cells, we found that free curcumin down-regulated its expression in BT-549 monolayers." (PMID 28956452, 2017). "The fact that AR is widely co-expressed with C1orf64 in breast cancer and negatively regulates the expression of this gene, raises the question of a possible biological significance for such a marked repression of C1orf64 by AR in breast cancer cells." (PMID 28915724, 2017). "This study investigated the network of genes that are co-expressed with androgen receptor (AR) to discover novel AR targets in breast cancer." (PMID 28915724, 2017). "Given that some studies have shown signs of activity for AR-signaling inhibitors, a number of additional trials are either planned or underway testing AR-directed therapies in breast cancer patients." (PMID 28085048, 2017). "Recently, attention to the AR in breast cancer research increased, with results supporting AR inhibitor as a treatment for AR+ breast cancer." (PMID 28262798, 2017). "We also emphasize the importance of prognostic implications of AR in breast cancers, potential therapeutic molecules, putative challenges, and related methodologies that deal with post-menopausal AR induced breast cancers." (PMID 29254284, 2017). "In conclusion, this study demonstrates subtype-specific differences in the effects of AR-515 phosphorylation in breast cancer patients." (PMID 28415597, 2017). "The androgen receptor (AR) is a critical transcription factor with prognostic value in breast cancer and prostate as well as in bladder carcinomas." (PMID 28122331, 2017). "Although the AR is expressed in 50–70% of all breast cancers, it is reported to be positive in 80–90% of all ER+ BC." (PMID 27923036, 2017). "Co-expressing AR in ERα-positive breast cancer improved disease-free survival (DFS) and overall survival (OS) significantly." (PMID 28474005, 2017). "AR and ER co-expressing breast cancers generally have better outcomes in terms of time to relapse (TTR), as well as disease specific survival (DSS) as noted from a study by Castellano and colleagues." (PMID 28245550, 2017). "It is notable that PIP is a key molecular target of AR that is widely expressed in luminal A, luminal B, and molecular apocrine subtypes of breast cancer and is necessary for cell cycle progression in breast cancer cells." (PMID 28915724, 2017).
breast carcinoma (continued). "Bioinformatics analysis of two datasets from breast cancer cell lines resulted in the identification of an AR-gene signature constituted of 98 genes that highly correlated with AR expression." (PMID 28915724, 2017). "AR has been reported to be expressed in 60–90% of sporadic breast cancer and is considered an independent prognostic factor of better outcome in ER-positive patients." (PMID 28863181, 2017). "We will also discuss some recent interesting findings on the second generation of AR antagonists for treatment of breast cancer." (PMID 28474005, 2017). "In view of a strong correlation between the expression of AR and each of the signature genes, it is likely that some of these genes are regulated by AR activation in breast cancer cells." (PMID 28915724, 2017). "It is well known that androgen can influence breast cancer cell growth by either aromatization to estrogens or through AR-dependent mechanisms." (PMID 28474005, 2017). "This study aims to further understand the role of androgens and AR activation in breast cancer by determining its effect on patient survival." (PMID 28415597, 2017). "Future studies are certainly required to uncover the detail mechanism of AR action in HER2 + breast cancer." (PMID 29109513, 2017). "The transcriptional studies were carried out using breast cancer cell lines T-47D (ER+/AR+, luminal A subtype) and MFM-223 (ER-/AR+, molecular apocrine subtype)." (PMID 28915724, 2017). "While MBC expresses many of the same biomarkers as female breast cancer, of those examined, we found only AR remained significant upon multivariate analysis, providing potential for AR blockade to be employed therapeutically." (PMID 28350011, 2017). "Similar results were obtained when the growth of HCC1954 and SKBR3 was analyzed using CCK-8 reagent, further supporting that knockdown of AR expression reduced the growth of HER2 + breast cancer cells." (PMID 29109513, 2017). "In this study we performed a novel radiosensitizer screen that identified anti-androgen therapy as a potentially effective strategy for the treatment of AR-positive radioresistant breast cancers." (PMID 28840192, 2017). "Gene expression profiling has also led to distinct molecular subtyping that is sometimes used to classify breast cancer, and these tumors seem to show variable rates of AR expression." (PMID 28245550, 2017). "The positive correlation of AR and C1orf64 expression in breast cancer can be explained by the fact that in order for AR and its coregulators to function together, both must be expressed in the same cells." (PMID 28915724, 2017). "Another study showed bicalutamide; an AR antagonist can block the growth of MDA-MB-453 human breast cancer cells by blocking HER2/HER3 signaling and downstream effectors PI3K/AKT." (PMID 29254284, 2017). "In breast cancer (BC), androgen receptor (AR) expression is related to estrogen receptor (ER) and/or progesterone receptor (PgR) expression." (PMID 28060723, 2017). "Our data revealed that inhibiting AR impairs the growth of HER2 + breast cancer cells in vitro and vivo, in comparable to the effect of trastuzumab." (PMID 29109513, 2017). "Results from this study suggest AR can in part activate HER2 signaling to drive the growth of HER2 + breast cancer cells in vitro and in vivo." (PMID 29109513, 2017). "After adjustments for age and tumor characteristics (model 1), there was slight evidence that patients with AR+ER− tumors had higher incidence of breast cancer-related death compared to patients with AR+ER+ tumors." (PMID 28643022, 2017). "The purpose of the present study was to explore the genetic expression patterns and associations between AR and FOXA1 by ER status determined from web-based breast cancer datasets." (PMID 29137314, 2017). "Herein, we report significant heterogeneity in AR RNA and protein expression levels in human breast cancer, including TNBC." (PMID 28840192, 2017).
breast carcinoma (continued). "Androgen receptor (AR) is frequently detected in breast cancers, and AR-targeted therapies are showing activity in AR-positive (AR+) breast cancer." (PMID 28957377, 2017). "On the other hand, in breast cancer patients where AR acts as an oncogenic driver, in that situation the anti-androgenic therapy would be more beneficial." (PMID 29254284, 2017). "The aim of this study was to elaborate on previous findings of a differential prognostic role for AR depending on ER status, using breast cancer mortality (BCM) as endpoint, in a population-based cohort from the Malmö Diet and Cancer Study." (PMID 28643022, 2017). "In ERα-positive breast cancer, AR is thought to antagonize the proliferative effect of ERα and in ERα-negative tumors, AR signaling has a proliferative role." (PMID 28903441, 2017). "AR is widely expressed in HER2 + breast cancer; however, its function in HER2 + breast cancer is unclear." (PMID 29109513, 2017). "There is evidence suggesting that AR expression is about 60% among early breast cancers and is more frequently expressed in ER-positive than ER-negative breast cancers." (PMID 28299476, 2017). "Specifically, this study looked at the odds ratios for overall survival (OS) and disease free survival (DFS) at 3 and 5 years for patients with AR expression, in which 4658 patients (60.5%) had breast cancers that were notably AR-positive." (PMID 28245550, 2017). "This negative regulation is further supported by the fact that C1orf64 has a profound repressive effect on the AR reporter activity in breast cancer cells." (PMID 28915724, 2017). "Nonetheless it is clear that routinely assessing AR status at the time of diagnosis for breast cancer should be encouraged that will allow the AR status along with ERα/PR and HER2 status to be used for selecting therapeutic treatment for breast cancer." (PMID 28474005, 2017). "Androgen receptor (AR) signaling has become increasingly important in understanding the biology of breast cancer, and serves as a potential therapeutic target in the era of precision medicine." (PMID 28245550, 2017). "Our results implicate androgen receptor as a mediator of radioresistance in breast cancer and identify androgen receptor inhibition as a potentially effective strategy for the treatment of androgen receptor-positive radioresistant tumors." (PMID 28840192, 2017). "In terms of co-receptor expression, ERα is known to be proliferative in breast cancer but ERβ is less understood, especially in relation to AR." (PMID 28245550, 2017). "In a Chinese study analyzing 116 patients from 1995 to 2008, men were found to have poorer outcomes if their breast cancers were AR-positive." (PMID 28245550, 2017). "Yet, the strong positive correlation between AR and BRCA1 should inspire future studies to explore AR signaling as a therapeutic target in familial breast cancers that have altered BRCA1 expression." (PMID 28863181, 2017). "Androgen receptor (AR) is expressed in 60% of breast cancers and is more frequently expressed in ERα-positive than in ERα-negative tumors." (PMID 28903441, 2017). "We first determined the expression levels of AR in various breast cancer cell lines (RNA and protein) and found significant heterogeneity in AR expression levels in breast cancer cell lines." (PMID 28840192, 2017). "Seventy to 80% of all breast cancers express the estrogen receptor (ER)α and 60-80% express the androgen receptor (AR)." (PMID 28977936, 2017). "Results from this analysis highlighted the pivotal role of miR-9-5p in breast cancer tumourigenesis and invasion through the negative regulation of the androgen receptor (AR) and oestrogen receptor (ER)." (PMID 28345661, 2017). "Current understanding of AR and AR signaling suggest potential for novel therapeutic targets for breast cancer." (PMID 28474005, 2017). "The presented data demonstrate that AR activation directly represses C1orf64 transcription in breast cancer cells." (PMID 28915724, 2017).
breast carcinoma (continued). "In fact, the mechanisms for the inhibition of ER activity by AR in breast cancer are not fully understood and one suggested mechanism is direct AR binding to a subset of estrogen response elements that can prevent E2-mediated activation of ER target genes." (PMID 28915724, 2017). "Here we will review the role of AR in different subtypes of breast cancers and elucidate its mechanisms." (PMID 28474005, 2017). "AR is expressed in up to 90% of estrogen receptor (ER) positive breast cancer, and to a lesser degree, human epidermal growth factor 2 (HER2) amplified tumors." (PMID 28245550, 2017). "Hence, inhibition of AR nuclear translocation by enzalutamide could directly prevent transcriptional activation of AR-induced tumor associated genes that lead to cell proliferation and metastasis in breast cancer." (PMID 28474005, 2017). "This study indicates that cohorts with larger sample sizes are needed to further elucidate the prognostic role of AR in ER− breast cancer." (PMID 28643022, 2017). "We also suggested that further studies in the area are urgently needed to use AR as a therapeutic target for post-menopausal women with breast cancers." (PMID 29254284, 2017). "In this review, we have highlighted multiple mechanisms on how AR is involved in breast cancer progression and its metastasis in ER+ breast tumors in post-menopausal women." (PMID 29254284, 2017). "The prognostic role of AR has consistently been described as favorable for breast cancer in general and within the estrogen receptor-α positive (ER+) subgroup." (PMID 28643022, 2017). "So these genes need to be checked by RNA-seq analysis between AR+ and AR knockout ER+ breast cancer cell line." (PMID 29254284, 2017). "Using breast cancer patient population treated at a single institute, the prognostic value of immunohistochemically determined AR and FOXA1 status was investigated." (PMID 29137314, 2017). "For AR positivity, many studies have adopted the standardized criteria for determining ER and PR positivity in breast cancer, defined as >1% positive cancer cells, which was also used in our study." (PMID 28067809, 2017). "AR confers good prognosis in estrogen receptor positive (ER+) breast cancer, but its role in ER-negative (ER−) breast cancer is unclear." (PMID 28643022, 2017). "Some studies also reported that AR induces cell proliferation, migration, and apoptosis in prostate and breast cancer through PTEN cell-signaling pathway." (PMID 29254284, 2017). "A Swedish population-based prospective cohort study assessing patients from 2002 to 2012 also showed a statistically significant improvement in DFS (at 6 years, approximately 90% versus 78%) in breast cancers co-expressing AR and ER." (PMID 28245550, 2017). "In this process, bioinformatics analysis of two large datasets from a broad range of breast cancer cell lines resulted in the identification of a combined AR-gene signature constituted of 98 genes that highly correlated with AR expression." (PMID 28915724, 2017). "The role of AR in breast cancer is evolving rapidly; a recent study showed that AR has a role in breast cancer development and metastasis." (PMID 29254284, 2017). "The identification of the AR signaling pathway in breast cancer has led to an interesting and growing field, especially in regards to basic and translational research." (PMID 28245550, 2017). "In summary, this study investigated the network of genes that are co-expressed with AR in breast cancer and identified C1orf64 as a novel AR target gene and coregulator in this disease." (PMID 28915724, 2017). "A previous in vivo study of AR function in metastasis of ER+ tumors used a breast cancer cell line xenograft and PDX models, which are very difficult to establish and require non-physiological hormone supplements." (PMID 29254284, 2017). "AR-targeting drugs such as bicalutamide and enzalutamide have been tested in clinical trials in breast cancer patients." (PMID 28957377, 2017).
breast carcinoma (continued). "For example, HR-negative and HER2-positive breast cancers seem to express AR in the range of 50%–60%; TNBC is generally between 20% and 40%." (PMID 28245550, 2017). "The fact that a well-known resistance mechanism to AR-directed therapy appears relevant to breast cancer provides further support for the importance of AR-signaling in breast cancer." (PMID 28085048, 2017). "For instance, a phase II trial with bicalutamide suggested potential benefits of targeting AR in AR-dependent, ER-independent breast cancer." (PMID 28474005, 2017). "On the basis of AR expression in breast cancer, a phase II study of the AR inhibitor enzalutamide in TNBC with AR expression is now in progress." (PMID 28060723, 2017). "In our study, overexpression of Lin28A introduced AR and c-myc expression, whereas knockdown of Lin28A inhibited AR and c-myc expression in ER-/Her2+ breast cancer cells." (PMID 27494865, 2016). "Collectively, these data reveal cell context-specific androgen-independent activation of AR-responsive reporters by type 3a and type 3b AR in prostate and breast cancer cells." (PMID 28035996, 2016). "Consistent with findings in previous studies and preclinical studies, we identified AR status as a prognostic marker for DFS in patients with breast cancer." (PMID 27285752, 2016). "No experimental data are available to ascertain an effect of AR in Snail family regulation in breast cancer cells." (PMID 26797644, 2016). "This is interesting because androgens are necessary precursors for estrogen synthesis and androgen receptor signaling itself has been demonstrated to increase cell proliferation and breast cancer progression." (PMID 27769065, 2016). "Some studies have reported that the AR expression is also related to the size of the tumor, the spread to lymph nodes in the armpit, certain kinds of histology, the stage of breast cancer and the status of the ER and PR." (PMID 29083379, 2016). "Our study demonstrates that Lin28A can activates androgen receptor via regulation of c-myc and promotes malignancy of ER−/Her2+ breast cancer." (PMID 27494865, 2016). "Multiple lines of evidence suggest that the AR is a favorable prognostic indicator in breast cancer and that AR agonists would be the preferred approach for choice of androgenic treatment for ER-positive breast cancer." (PMID 27918430, 2016). "To clarify the mechanism through which androgens down-regulate miR-21 expression in breast cancer cells, we verified the binding of AR on the ARE sequence within the miR-21 promoter." (PMID 26862856, 2016). "Our study also provides a rationale for testing a CHKA inhibitor in 60% to 70% cases of molecular apocrine-type breast cancers that rely on AR signaling." (PMID 26657335, 2016). "Calcitriol and/or its analogs induce the up-regulation of VDR and AR as well as the down-regulation of ERα in prostate and/or breast cancer cells." (PMID 27973439, 2016). "Significant differences in AR expression patterns among different breast cancer subtypes are observed." (PMID 27285752, 2016). "Although the protective role of androgen receptor (AR) in breast cancer (BC) is well established, the mechanisms involved remains largely unexplored." (PMID 26862856, 2016). "Levels of androgen receptor were assessed in 5 breast cancer cell lines, BT-549, HS578T, MCF7, MDA MB 231, and T47D." (PMID 27015557, 2016). "Analysis of OS demonstrated similar observations according to the subtypes and AR expression status of the breast cancer." (PMID 26757422, 2016). "Apocrine breast cancers, a subset of ER-negative and AR-positive breast cancers, show androgen-stimulated growth." (PMID 28035996, 2016). "Collectively, these data demonstrate that Lin28A increased AR and c-myc expression in ER-/Her2+ breast cancer cells." (PMID 27494865, 2016). "Altogether, these results indicate that AR is required to down regulate miR-21 expression and that it is a general mechanism occurring in breast cancer tissue." (PMID 26862856, 2016).